WNT3A (Wnt family member 3A)
Diseases named in the same sentence as WNT3A in open-access papers (continued):
Sharing a sentence is not in itself a finding about the gene and the disease.
meningioma (2 papers, 2023 to 2024). A generally slow growing tumor attached to the dura mater. "Co-transfection of the TOP-Flash Tcf/Lef Wnt luciferase reporter and treatment with recombinant Wnt3a or vehicle control revealed Merlin suppression attenuated Wnt signaling in meningioma cells." (PMID 36993679, 2023). "In the presence of Wnt3a, overexpression of Merlin activated the Wnt pathway in meningioma cells regardless of endogenous Merlin status." (PMID 39251601, 2024). "In the absence of Wnt3a, Merlin overexpression did not activate the Wnt pathway in meningioma cells with or without endogenous Merlin, but endogenous Merlin suppression attenuated Wnt signaling." (PMID 39251601, 2024).
metastatic tumors (2 papers, 2014 to 2019). "In summary, wnt3a and wnt5a expression is high in primary and metastatic tumors in CRC with a high concordance rate." (PMID 24564183, 2014). "Moreover, immunohistochemistry (IHC) staining of primary and metastatic tumors showed that PTK6 reversed the effects of PSPC1 on downregulating E-cadherin and upregulating vimentin, β-catenin, c-Myc and Wnt3a." (PMID 31844057, 2019).
nasopharyngeal carcinoma (2 papers, 2022). A carcinoma arising from the nasopharyngeal epithelium. "Mechanism research confirmed CASC9 regulated the malignant biological behavior of nasopharyngeal carcinoma cells by targeting miR-497-5p/Wnt3a/β-catenin signaling pathway." (PMID 35419295, 2022). "CASC9 may regulate the malignant biological behavior of nasopharyngeal carcinoma cells by targeting miR-497-5p/Wnt3a/β-catenin signaling pathway." (PMID 35419295, 2022). "In order to understand whether miR-497-5p affects Wnt3a/β-catenin pathway, we detected the expression of Wnt3a/β-catenin pathway related proteins after miR-497-5p overexpression in nasopharyngeal carcinoma cells by Western blot." (PMID 35419295, 2022). "In vitro and in vivo studies on the radiation resistance model in nasopharyngeal carcinoma, we found that radiation can induce the overexpression of Wnt canonical signaling pathways (represented by Wnt3a) and Wnt non-canonical signaling pathways (represented by Wnt5A)." (PMID 35517407, 2022).
osteoarthritis (2 papers, 2022 to 2025). A noninflammatory degenerative joint disease occurring chiefly in older persons, characterized by degeneration of the articular cartilage, hypertrophy of bone at the margins and changes in the synovial membrane. "A distinct mode of inhibition of Wnt signaling by dioscin was reported in an osteoarthritis mouse model, where mRNA expression of Wnt3a and β-catenin, sharply increased upon induction of the disease by iodoacetate, were counteracted by the compound treatment." (PMID 40427472, 2025). "In recent studies of osteoarthritis, Wnt3a was confirmed as a direct target of miR-497-5p, and expression of miR-497-5p was negatively correlated with Wnt3a level in cartilage." (PMID 35419295, 2022). "In primary rat chondrocytes induced by IL-1β, it additionally promoted GSK3β phosphorylation and decreased Wnt3a levels, as well as those of WISP1, a target gene, and crosstalk with Hippo/YAP, thus contributing to protective effects in osteoarthritis by preventing excessive ECM degradation." (PMID 40427472, 2025).
pulmonary tuberculosis (2 papers, 2016 to 2022). A bacterial infection that affects the lungs and is caused by Mycobacterium tuberculosis. "This review focuses on the regulation of Wnt5a, Wnt3a, and the recently identified Wnt6 and their functional role in bacterial infections with a primary focus on pulmonary tuberculosis, a leading infectious cause of morbidity and mortality worldwide." (PMID 28082976, 2016).
Sepsis (2 papers, 2015 to 2019). Sepsis is defined as life-threatening organ dysfunction caused by a dysregulated host response to infection. "Despite GSK-3β inhibitor is recognized as a potential treatment of sepsis, our data demonstrated that many components of canonical Wnt3a signaling were also affected in the lung of rats with endotoxic shock." (PMID 26218875, 2015). "Indeed, our study showed that the expression of Wnt3a and β-catenin were significantly down-regulated in the lung of LPS-induced sepsis animals, indicating that the reduction of Wnt3a and β-catenin in the lung could be associated with lung inflammation and injury in endotoxemia." (PMID 26218875, 2015). "In fact, cumulative evidence supports the role of the Wnt pathway in the regulation of the macrophage-mediated inflammatory response in sepsis, in which Wnt3a and Wnt6 reduce TNFα secretion and promote the differentiation towards an M2 anti-inflammatory phenotype attenuating the immune response." (PMID 31665078, 2019).
steatosis (2 papers, 2016 to 2021). Increased lipid within the cytoplasm of cells. "This study demonstrated that 8 weeks of exercise prevented lipotoxicity-induced hepatic injury, inflammation, and steatosis by inhibiting HMGCS2, subsequently ameliorating apoptosis and normalizing the Wnt3a/β-catenin pathway." (PMID 33647884, 2021). "NAFLD mice showed evident steatosis, fibrosis, and liver injury, and an increased expression of HMGCS2, Wnt3a/ β-catenin, and phosphorylated (p)-AMPK in the liver." (PMID 33647884, 2021).
virus infection (2 papers, 2013 to 2023). "To this end, we investigated whether the Delta (B.1.617.2) and Omicron (B.1.1.529) variants also employ Wnt3a for virus infection." (PMID 38203386, 2023). "Collectively, our study identified Wnt3a as an important host factor that facilitates ACE2-mediated virus infection." (PMID 38203386, 2023). "We discovered that the upstream component of the pathway, Wnt3a, is important for SARS-CoV-2 infection and inhibition of Wnt3a secretion by the treatment of LGK-974 significantly reduced virus infection." (PMID 38203386, 2023). "This suggests that Wnt3a contributes to ACE2-mediated virus infection." (PMID 38203386, 2023). "Based on the GTEx portal, Wnt3a expression in the lungs is higher than ACE2 expression, hinting that Wnt3a may be used to compensate for low ACE2 expression upon virus infection." (PMID 38203386, 2023). "It is plausible that Wnt3a levels may also be considered as a biomarker of enhanced virus infection; however, extensive investigation on the dynamic regulation of Wnt3a expression during viral infection using patient plasma is necessary." (PMID 38203386, 2023). "Our findings suggest that the Wnt3a/β-catenin pathway mediates ACE2 transcription and may contribute to ACE2-mediated virus infection." (PMID 38203386, 2023).
acute kidney injury (1 paper, 2019). Sudden and sustained deterioration of the kidney function characterized by decreased glomerular filtration rate, increased serum creatinine or oliguria. "We investigated the relevance of D2R′s modulation of Wnt3a expression and cell proliferation within a disease context using the ischemia/reperfusion-injury (I/R) model of acute kidney injury." (PMID 31727925, 2019).
acute lymphoblastic leukemia (1 paper, 2015). Leukemia with an acute onset, characterized by the presence of lymphoblasts in the bone marrow and the peripheral blood. "For example, Wnt3a suppresses the growth and proliferation of the lung and lacrimal gland, induces B-cell precursor acute lymphoblastic leukemia (B-ALL) cell death, and suppresses the proliferation of several B-ALL cell lines." (PMID 26369691, 2015).
acute myeloid leukemia (1 paper, 2025). Acute myeloid leukemia (AML) is a group of neoplasms arising from precursor cells committed to the myeloid cell-line differentiation. "In vertebrates, Wnt-3a is a hematopoietic growth factor that promotes acute myeloid leukemia (AML) clone expansion." (PMID 39940651, 2025).
adenoma (1 paper, 2021). A neoplasm arising from the epithelium. "In addition, we found variants in genes implicated in Wnt signalling, such as LRP5, WNT3A, and SFRP2, which shows a significantly increased level of methylation in adenomas." (PMID 34843512, 2021).
airway hyperresponsiveness (1 paper, 2023). "Pycr1 deficiency restrained inflammation, airway hyperresponsiveness (AHR), and EMT, which may be associated with the regulation of mitochondrial damage, cellular metabolomic imbalance, and WNT3a/β-catenin and AKT/mTORC1 signaling activation." (PMID 37432745, 2023).
Aleutian disease (1 paper, 2024). "From this, we identified several candidate genes contributing to the growth and feed efficiency (ARID1B, APPL1, TOX, and GPC5), reproduction (GRM1, RNASE10, WNT3, WNT3A, and WNT9B), pelt quality (MYO10, and LIMS1), and Aleutian disease tests (IFNGR2, APEX1, UBE3A, and STX11)." (PMID 38167844, 2024).
ankylosis (1 paper, 2022). Fixation and immobility of a joint. "One of the mechanisms underlying the inhibitory effect of PDGF-BB on ankylosis could be the suppression of osteoblastic differentiation from PDL cells; PDGF-BB suppressed osteocalcin-positive cells in vivo, and Wnt3a induced bone marker expressions in PDL cells in vitro." (PMID 35217688, 2022).
autism (1 paper, 2021). Persistent deficits in social interaction and communication and interaction as well as a markedly restricted repertoire of activity and interest as well as repetitive patterns of behavior. "Comparisons between TBBPA-DBPE and TCEP demonstrated that TBBPA-DBPE-induced dysregulation of WNT3A, a member of Wnt pathway known to impact neurodevelopment and neurodevelopmental disorders such as autism." (PMID 33898466, 2021).
Barrett’s metaplasia (1 paper, 2019). "Both findings, the increase in Dkk1 and the decrease in Wnt3a support Wnt-independent β-catenin activation in Barrett’s esophagus." (PMID 30841855, 2019). "Immunohistochemical staining in Barrett’s metaplasia, HGIN, and adenocarcinoma of embedded specimens for WNT3A revealed a significant higher staining intensity of WNT3A positive cells in squamous epithelium (SQ) compared to intestinal metaplasia, HGIN and adenocarcinoma cells." (PMID 30841855, 2019).
bone sarcoma (1 paper, 2015). A sarcoma that arises from the bone. "Stimulation of the Wnt/β-catenin by Wnt3a markedly triggered c-Myc expression in bone sarcoma cells, whereas downregulation of β-catenin/TCF signaling resulted in reduction of c-Myc and cyclin D1 levels and decreased cell proliferation." (PMID 25999350, 2015). "In addition, Wnt3a stimulation can readily promote bone sarcoma cell survival." (PMID 25999350, 2015). "Stimulation of Wnt/β-catenin signaling with Wnt3a or GSK-3β inhibitor enhanced the proliferation and survival of bone sarcoma cells, whereas antagonism of this pathway with dnTCF4 or siLEF1 had the exact opposite effect." (PMID 25999350, 2015). "Activation of Wnt/β-catenin signaling with Wnt3a or GSK-3β inhibitor drives the proliferation of bone sarcoma cells, whereas downregulation of activated Wnt signaling with dnTCF4 or siLEF1 suppresses bone sarcoma proliferation and induces cell cycle arrest." (PMID 25999350, 2015).
cerebral infarction (1 paper, 2025). An ischemic condition of the brain, producing a persistent focal neurological deficit in the area of distribution of the cerebral arteries. "Wnt-3a protein administration leads to Gsk3b dephosphorylation, reducing cerebral infarction and neuronal apoptosis through the Foxm1 pathway." (PMID 40529227, 2025).
cervical intraepithelial neoplasia (1 paper, 2021). "Piwil2 reprograms HPV-infected reserve cells in the cervix into tumor-initiated cells (TICs) and upregulates Wnt3a expression sequentially, which leads to cervical intraepithelial neoplasia (CIN) and ultimately squamous cell carcinoma (SCC)." (PMID 34257574, 2021).
Charcot arthropathy (1 paper, 2022). "In T2DM patients who had developed Charcot arthropathy WNT3A and WNT5A gene expression was down-regulated by 89 and 58% compared to healthy controls (p < 0.0001)." (PMID 35436882, 2022). "For the first time significant changes in gene expression of the Wnt signaling pathway – namely WNT3A, WNT5A, TCF7L2 and osteocalcin- in the bone of patients suffering from T2DM and following Charcot arthropathy could be shown." (PMID 35436882, 2022). "In this study, we could show a significant downregulation of WNT3A and WNT5A in patients suffering from T2DM induced Charcot arthropathy with the need of surgical treatment." (PMID 35436882, 2022).
chronic heart failure (1 paper, 2020). "Aberrant Wnt/β-catenin signaling causes a shift in muscle fiber type through the interaction of Wnt3a with FOXO1 in chronic heart failure in mice." (PMID 33334063, 2020).
chronic lymphocytic leukemia (1 paper, 2013). "miR-15a, along with miR-16, is commonly deleted in human chronic lymphocytic leukemia and known to target multiple oncogenes, including BCL2, MCL1, CCND1, and WNT3A." (PMID 23557329, 2013).
Duchenne muscular dystrophy (1 paper, 2021). Duchenne muscular dystrophy (DMD) is a neuromuscular disease characterized by rapidly progressive muscle weakness and wasting due to degeneration of skeletal, smooth and cardiac muscle. "Skeletal muscle SCA-1+ cells (FAPs) are abundant in the muscles of the mdx mice (model of the Duchenne Muscular Dystrophy (DMD)), and WNT3a treatment promotes their proliferation and collagen expression both in vitro and in vivo." (PMID 34210364, 2021).
Ewing sarcoma (1 paper, 2019). A small round cell tumor that lacks morphologic, immunohistochemical, and electron microscopic evidence of neuroectodermal differentiation. "The analysis of the secretome of Wnt3a-activated Ewing sarcoma cells has revealed an increased secretion of proteins implicated in the composition and the structure of the extracellular matrix." (PMID 31370265, 2019). "Finally, Ewing sarcoma in response to Wnt3a stimulation can modify the acellular TME by increasing the secretion of proteins involved in the composition of the extracellular matrix." (PMID 31370265, 2019). "Indeed, LGR5 is highly expressed in aggressive Ewing sarcoma and CSCs and the binding of RSPO-2 on LGR5 was able to potentiate Wnt3a-induced canonical Wnt signaling." (PMID 31370265, 2019).
fibrosarcoma (1 paper, 2024). A malignant mesenchymal fibroblastic neoplasm affecting the soft tissue and bone. "We expressed WNT4 or WNT3A fused to C-terminal BirA biotin ligase in HT1080 WT and porcupine O-acetyltransferase (PORCN)-knockout (PKO) cells (Wnt-responsive fibrosarcoma cell line), and ILC cell line MDA MB 134VI (MM134)." (PMID 38112643, 2024).
fibrosis (1 paper, 2025). the formation of excess fibrous connective tissue in an organ or tissue in a reparative or reactive process. "The Wnt3a/β‐catenin signalling pathway plays a pivotal role in cardiac remodelling, cardiac fibrosis and apoptosis." (PMID 40407710, 2025).
gastric adenocarcinoma (1 paper, 2018). "Moreover, treatment of Wnt3a, the activator of Wnt signaling pathway, partially recovers the proliferation defect observed in LGR5 knockdown gastric adenocarcinoma cells." (PMID 30089773, 2018).
gastric tumor (1 paper, 2025). "Furthermore, WNT3A-induced WNT pathway activation synergizes with SMARCD3 to enhance EMT progression, underscoring the complex interplay of signaling cascades in gastric tumor biology." (PMID 41228321, 2025).
glaucoma (1 paper, 2022). Increased pressure in the eyeball due to obstruction of the outflow of aqueous humor. "Wnt3a/β-catenin and PI3K/AKT pathways are considered proinflammatory and profibrotic signaling pathways that are activated by reactive oxygen species, which play an important role in the pathogenesis of glaucoma." (PMID 35456388, 2022).
glomerulosclerosis (1 paper, 2025). A hardening of the kidney glomerulus caused by scarring of the blood vessels. "In addition, oxidative stress is considered to play a crucial role in promoting the activation of the Wnt3a/β-catenin pathway in podocytes, thereby providing a potential molecular mechanism for podocyte injury and subsequent glomerulosclerosis." (PMID 39028478, 2025). "Therefore, our data support the hypothesis that the activation of the Wnt3a/β-catenin signaling pathway mediates podocyte injury, which is a key process leading to glomerulosclerosis development." (PMID 39028478, 2025).
hemorrhagic stroke (1 paper, 2020). A stroke caused by a bleed on the brain. "Similar to ischemic and hemorrhagic stroke, several studies were interested in assessing the effects of Wnt ligands in developing TBI therapies, with an emphasis on Wnt3a." (PMID 33071819, 2020).
Hydrocephalus (1 paper, 2024). Hydrocephalus is an active distension of the ventricular system of the brain resulting from inadequate passage of CSF from its point of production within the cerebral ventricles to its point of absorption into the systemic circulation. "Based on observations of the expression of Wnt1/Wnt3a mRNA and protein levels in IVH rats treated with DFX, some scholars speculated that iron might promote the subarachnoid fibrosis and hydrocephalus after IVH by activation of the Wnt signaling pathway." (PMID 37208490, 2024).
hyperlipidemia (1 paper, 2020). "Previous studies have reported that statins may improve hyperlipidemia and enhances femoral head neovascularization through suppresses PPARγ expression and activates Wnt3a/LRP5/b-catenin/RUNX2 signaling pathway in steroid-induced animal models." (PMID 32509867, 2020).
Hypodontia (1 paper, 2023). The absence of five or less teeth from the normal series by a failure to develop. "Based on the results of this study, we can assume that WNT3A also contributed to the formation of NSCL/P and hypodontia." (PMID 38031027, 2023). "The D1S160 marker was used to confirm LOH on chromosome 1q32.2-1q42.13, which includes the WNT3A gene in 20 NSCL/P and noncleft individuals with or without hypodontia." (PMID 38031027, 2023).
hypospadias (1 paper, 2024). Hypospadias is the displacement of the urethral meatus on the ventrum of the penis. "We utilized RT‐PCR and Western blot techniques to investigate the Wnt signaling pathway and observed a significant reduction in both mRNA and protein levels of SOX9, Wnt3a, LEF1, GSK3β, NF‐κB, TCF1, and cyclin D1 in the samples of hypospadias." (PMID 40626133, 2024).
ileitis (1 paper, 2020). "Through this pathway, TcdA was shown to inhibit intestinal crypt cell proliferation in a mouse model of C. difficile-induced disease-like ileitis despite Wnt3a upregulation observed in the crypts and lamina propria cells, which were insufficient to induce Wnt/β-catenin activation." (PMID 32983019, 2020).
infertile (1 paper, 2014). "Materials and Methods: WNT3a protein concentration and GSK3-β gene expression levels were measured and compared between two groups of infertile men." (PMID 25031575, 2014).
inflammatory bowel disease (1 paper, 2015). A spectrum of small and large bowel inflammatory diseases of unknown etiology. "As the release of Wnt3a increases in response to gut mucosa injury and inflammatory bowel diseases, the activation of canonical signaling pathway by Wnt3a could be hypothesized as an active mechanism in ENS." (PMID 25644719, 2015). "Recently, several studies have implied the involvement of canonical Wnt Frizzled signaling in inflammatory bowel disease (IBD), as a significant increased expression of Wnt3a and Frizzled receptors are observed." (PMID 25644719, 2015). "In our study, the binding specificity of Frizzled 9 with Wnt3a was demonstrated in ENS compartment and suggested the involvement of FZD9 in neuronal response to inflammation in light of the evidence that a significant increase of Wnt3a and FZD9 is observed in inflammatory bowel diseases." (PMID 25644719, 2015).
intrahepatic cholangiocarcinoma (1 paper, 2022). A carcinoma that arises from the intrahepatic bile duct epithelium in any site of the intrahepatic biliary tree. "Downregulation of SALL4 contributed to a decrease in B-cell-specific Moloney murine leukemia virus integration site 1 (Bmi-1) expression and inactivated the Wnt3a/β-catenin signaling pathway in intrahepatic cholangiocarcinoma (ICC)." (PMID 35216168, 2022).